IGKV1-9 (immunoglobulin kappa variable 1-9)
Description:
V region of the variable domain of immunoglobulin light chains that participates in the antigen recognition. Immunoglobulins, also known as antibodies, are membrane-bound or secreted glycoproteins produced by B lymphocytes. In the recognition phase of humoral immunity, the membrane-bound immunoglobulins serve as receptors which, upon binding of a specific antigen, trigger the clonal expansion and differentiation of B lymphocytes into immunoglobulins-secreting plasma cells. Secreted immunoglobulins mediate the effector phase of humoral immunity, which results in the elimination of bound antigens. The antigen binding site is formed by the variable domain of one heavy chain, together with that of its associated light chain. Thus, each immunoglobulin has two antigen binding sites with remarkable affinity for a particular antigen. The variable domains are assembled by a process called V-(D)-J rearrangement and can then be subjected to somatic hypermutations which, after exposure to antigen and selection, allow affinity maturation for a particular antigen.
Synonyms: IGKV19; L8
Gene: Immunoglobulin variable (V) gene on chromosome 2 (89,009,982 to 89,010,515, reverse strand). Ensembl gene ENSG00000241755.
Subcellular location: Secreted; Cell membrane
Gene Ontology:
Biological process: immune response
Cellular component: extracellular region; immunoglobulin complex; plasma membrane
Homologues: Orthologues: mouse Igkv15-103 (74% identical). Paralogues in human: IGKV1D-13 (93% identical), IGKV1-12 (91% identical), IGKV1-39 (91% identical), IGKV1D-39 (91% identical), IGKV1-17 (91% identical), IGKV1-27 (91% identical), IGKV1-5 (91% identical), IGKV1D-12 (91% identical), IGKV1D-16 (91% identical), IGKV1-16 (90% identical), IGKV1-6 (89% identical), IGKV1-8 (89% identical), and 81 more.
Diseases named in the same sentence as IGKV1-9 in open-access papers:
IGKV1-9 is named in the same sentence as 3 diseases in open-access papers, as found by Europe PMC text mining. Sharing a sentence is not in itself a finding about the gene and the disease.
IGKV1-9 shares sentences with these, for which no sentence is quoted: diabetes (1 paper); liver diseases (1); tumor (1).